CLDN2 (claudin 2)
Diseases named in the same sentence as CLDN2 in open-access papers (continued):
Sharing a sentence is not in itself a finding about the gene and the disease.
Sepsis (11 papers, 2019 to 2025). Sepsis is defined as life-threatening organ dysfunction caused by a dysregulated host response to infection. "Pre-clinical studies of sepsis demonstrate increased permeability is associated with upregulation of jejunal claudin-2 and claudin-5, along with downregulation of occludin and JAM-A." (PMID 40098052, 2025). "In a murine model following cecal ligation and puncture surgery, sepsis induction led to increased claudin-2 expression and decreased occludin expression." (PMID 40284216, 2025). "First, the role of upregulated claudin-2 seen in septic patients was examined in mice with intra-abdominal sepsis." (PMID 40098052, 2025). "Further, ileal claudin-2 expression increased in samples from patients with sepsis from abdominal perforation compared to age and sex matched patients who underwent elective intestinal resection while claudin-15, another pore-forming protein decreased." (PMID 40098052, 2025). "LncRNA NKILA silencing protected HK-2 cells from sepsis-mediated AKI by decreasing CLDN2 through sponging miR-140-5p." (PMID 37215112, 2023). "Notably, claudin-2 deletion improved survival in murine sepsis demonstrating a mechanistic link between TJ alteration and mortality." (PMID 40098052, 2025). "Within functional analyses, the deletion of claudin-2 reduced gut permeability and attenuated intestinal inflammation, whereas an occludin blockade exacerbated gut hyperpermeability with increased bacteremia during sepsis." (PMID 40284216, 2025). "However, the combination of butyrate and active 1,25D3 attenuated the increase in zonulin and claudin-2 protein expression in the cecal tissue of mice that had undergone chemotherapy and developed gut-derived P. aeruginosa sepsis." (PMID 38790988, 2024). "Similarly, the expression of ZO-1, Occludin, Claudin-2, detected by immunohistochemistry, was increased in the intestinal tissue in Card9−/−-sepsis mice treated with Ad-Ripk2 compared with Card9−/−-sepsis mice." (PMID 35618701, 2022). "Moreover, we detected substantially decreased expression of tight junction proteins in Card9−/−-sepsis mice compared with WT-sepsis mice, including ZO-1, occludin and Claudin-2." (PMID 35618701, 2022). "However, miR-140-5p could target CLDN2 to promote cell viability and inhibit apoptosis, autophagy and inflammation in lipopolysaccharide induced sepsis model." (PMID 36855217, 2023). "Mechanistically, claudin-2 and junctional adhesion molecule (JAM)-A are increased by sepsis, whereas claudin-5 and occludin are decreased by sepsis." (PMID 30923621, 2019). "Reduced claudin-2 expression in the intestinal epithelium and an elevation in claudin-2 protein in the urine were shown to correlate with the severity of NEC in a small study of human neonates, and was shown to be independent of other conditions including sepsis, medication use, or ventilation." (PMID 33492576, 2021).
Salmonella Infections (10 papers, 2013 to 2024). Infections with bacteria of the genus SALMONELLA. "Recently, we observed that Salmonella infection induced significantly enhanced zonulin and claudin-2, resulting in an increased bacterial invasion and translocation." (PMID 38397855, 2024). "Salmonella infection induced significantly enhanced claudin-2, resulting in an increased bacterial invasion and translocation." (PMID 36678175, 2023). "Salmonella infection considerably boosted Claudin-2 expression, leading to a beneficial environment for bacterial invasion and translocation." (PMID 36678175, 2023). "The down-regulation of ZO-1 and CLDN-5 and the up-regulation of CLDN-2 due to Salmonella infection were eliminated in the LAC + SAL group." (PMID 29396554, 2018). "Taken together, our data showed that claudin-2 is elevated in the colon in the early stage of Salmonella infection." (PMID 23505542, 2013). "We further found that the claudin-2 mRNA level in the colon was upregulated by Salmonella infection in vivo, whereas the other TJ proteins, claudin-3 and 7, were not changed by Salmonella infection." (PMID 23505542, 2013). "In 4 replicated groups, we clearly showed that claudin-2 protein was increased in both soluble and insoluble fractions after Salmonella infection." (PMID 23505542, 2013). "Interestingly, recent studies demonstrated a link between downregulation of VDR and overexpression of CLDN2 in Salmonella infection." (PMID 34445577, 2021). "However, the Salmonella infection downregulated the expression of claudin-2 in the colon of all S. Typhimurium-infected groups." (PMID 33333934, 2020). "In addition, Salmonella infection significantly increased the expression of Cldn-2 protein both in in vitro and in vivo model studies and modulated the localization of junctional Cldn2 protein." (PMID 28694783, 2017). "To determine whether claudin-2 is changed in the early stage of Salmonella infection, we tested the expression of claudin-2 in the colon 2, 4, 6, and 8 hours postinfection." (PMID 23505542, 2013). "In comparison with the NC group, Salmonella infection (the SAL group) significantly decreased mRNA levels of ZO-1 and CLDN-5 and increased the mRNA level of CLDN-2 (P < 0.05)." (PMID 29396554, 2018). "However, it is unknown how the leaky protein claudin-2 is influenced by Salmonella infection." (PMID 23505542, 2013). "However, it is unknown whether claudin-2 is influenced by Salmonella infection." (PMID 23505542, 2013). "The protein level of Claudin‐2 was significantly increased by Salmonella infection, whereas Claudin‐7 was not altered in the infected organoids." (PMID 25214524, 2014). "In contrast, claudin-2 was increased by Salmonella infection in cells without siRNA or with control siRNA." (PMID 23505542, 2013). "Salmonella induced reduction of the TER in both cells with normal claudin-2 expression (447.3 Ω.cm2) and with low cluadin-2 (840 Ω.cm2) at 30 minutes postinfection: Salmonella infection reduces TER values to around 50% initial values in both cells, regardless of the claudin-2 level." (PMID 23505542, 2013).
pancreatitis (9 papers, 2015 to 2024). Inflammation of the pancreas. "However, T (TT) genotypes associate with atypical localization of claudin-2 to the basolateral membrane of acinar cells and associate with the development of pancreatitis." (PMID 30524475, 2018). "Interestingly, we found no mutations that passed quality control or the expected segregation pattern, in genes known to be associated with pancreatitis such as PRSS1, CFTR, SPINK, CPA1, CTRC, CLDN2, and PLINP." (PMID 36699452, 2022). "Other genetic factors related to pancreatitis are Calcium Sensing Receptor (CASR), Claudin 2 (CLDN2), Carboxyl Ester Lipase (CEL), Cathepsin B (CTSB), Myosin IXB (MYO9B), Ubiquitin Protein Ligase E3 Component N-Recognin 1 (UBR1), and Fucosyltransferase 2 (FUT2)." (PMID 36434531, 2022).
celiac disease (8 papers, 2015 to 2024). An autoimmune genetic disorder with an unknown pattern of inheritance that primarily affects the digestive tract. "First and foremost, claudin-2 abundance increases in various inflammatory diseases, such as CD, UC and celiac disease." (PMID 30728783, 2018). "The aberrant expression of claudin-2 has been found in many diseases such as IBD, Celiac disease, and HIV-enteropathy." (PMID 28106723, 2017). "An increased claudin 2 expression results in a decreased TEER and increased paracellular permeability, and this can be observed in different intestinal diseases like IBD or celiac disease." (PMID 38338808, 2024). "The level of claudin-2 is increased in the intestinal epithelium of patients with IBS with diarrhea (IBS-D), UC, and celiac disease, an observation that may explain why such patients experience diarrhea." (PMID 33803334, 2021).
gastric cancer (8 papers, 2013 to 2024). A primary or metastatic malignant neoplasm involving the stomach. "Interestingly, a recent study indicated that CagA disrupts tight junctions by increasing the CDX2-dependent targeting of Claudin-2 in gastric carcinoma cells and causes significant changes in the morphology and activity of these cells." (PMID 35331316, 2022). "Similar upregulation of claudin-2 expression is now reported in lung, liver, stomach cancer tissues and to promote breast cancer metastasis." (PMID 29152115, 2017). "Accordingly, significant elevation in claudin-2 expression has been reported in colorectal, hepatocellular, and gastric cancers." (PMID 29152115, 2017). "The positive expression rates of claudin-2 in gastric cancer tissues and adjacent tissues were 25% and 68% respectively (P < 0.001)." (PMID 23919729, 2013). "However, in our present work the cytoplasmic staining of claudin-11 was strong in gastric cancer tissues and weak in adjacent tissues, reveals that claudin-11 may be a positive diagnostic marker in gastric cancer which was different with claudin-2 and claudin-6." (PMID 23919729, 2013). "In our study, claudin-2 expression was evaluated in the cytoplasm or membranes of 40 gastric cancers tissues and 28 specimens containing gastric tissue adjacent to the carcinoma." (PMID 23919729, 2013). "The expression of claudin-2 in gastric cancer tissues was significantly lower than in adjacent tissues (The Chi-square test/Chi-Square Goodness-of-Fit Test, P < 0.001)." (PMID 23919729, 2013). "Positive expression of claudin-2 protein was found in 25.0% (10/40) of gastric carcinoma tissues and in 67.8% (19/28) of adjacent tissues." (PMID 23919729, 2013). "Similarly, claudin-2 were selective down-regulated in gastric cancer compared with corresponding cancer adjacent tissues in our present data." (PMID 23919729, 2013). "Thus in our study, the expression of claudin-2, and claudin-6 was down regulated in gastric cancer tissue while the expression of claudin-11 was up regulated." (PMID 23919729, 2013). "Our present data observes that claudin-2 and claudin-6 were both down-regulated and may be concurrently expressed in gastric cancer, reveals that claudin-2 and claudin-6 may act as synergistic tumor suppressors in gastric cancer." (PMID 23919729, 2013). "Thus, the objective of this study was to examine the expression of claudin-2,-6, and −11 in gastric carcinoma and adjacent tissue which have been less well studied." (PMID 23919729, 2013). "Although an increase in claudin-2 expression was found, claudin-2 expression is ubiquitously present in normal and neoplastic tissue, so the benefit of potential therapy against claudin-2 (as in the case of claudin-18.2 in advanced gastric carcinoma) appears to be restricted." (PMID 36232536, 2022). "Upregulation of claudin-2 (CLDN-2) expression in human lung, liver, colon and stomach cancer tissues is reported." (PMID 36961882, 2023). "In addition, claudin-2 and claudin-6 may be concurrently expressed in gastric cancer." (PMID 23919729, 2013). "The present work infers that the expression altered of claudin-2, claudin-6, and claudin-11 between human gastric cancers and adjacent non-neoplastic tissues and does not correlate with their clinical behavior." (PMID 23919729, 2013). "Our study provides the first evidence that claudin-2,-6, and −11 protein expression varies between human gastric cancers and adjacent non-neoplastic tissues." (PMID 23919729, 2013). "For example, reports have shown that CLDN2, CLDN7, and CLDN9 contribute to the enhanced invasion and migration of gastric cancer (GC) cells." (PMID 39199633, 2024).
Hypercalciuria (6 papers, 2020 to 2025). "Kidney-specific claudin-2 KO causes transient hypercalciuria." (PMID 41066193, 2025). "To elucidate the role of kidney claudin-2 in the pathogenesis of hypercalciuria and kidney stone disease, we generated floxed Cldn2 mice and developed renal tubule-specific Cldn2 conditional KO mouse models." (PMID 41066193, 2025). "Prior work characterizing mice with global claudin-2 knockout (Cldn2-KO mice) revealed lifetime hypercalciuria, intestinal calcium hyperabsorption, and development of nephrocalcinosis resembling Randall’s plaques." (PMID 41321305, 2025). "Mice with kidney tubule–specific Cldn2 deletion experienced only transient hypercalciuria just after birth, followed by normalization." (PMID 41321305, 2025). "In conclusion, kidney-specific claudin-2–KO mice were normocalciuric aside from a transient period of hypercalciuria in early life, yet developed papillary nephrocalcinosis with advancing age." (PMID 41066193, 2025). "The Cldn2-KO mouse thus modeled the early steps in human idiopathic hypercalciuria and calcium oxalate stone formation." (PMID 41321305, 2025). "Ncx1-kidney-specific KO mice and Cldn2 KO mice are genetic mouse models of hypercalciuria due to a primary defect in renal tubular (respectively DCT and proximal tubule) calcium transport." (PMID 36227903, 2022). "Cldn2 KO mice exhibit hypercalciuria and increased net intestinal Ca2+ absorption, while Cldn12 KO mice do not have an overt Ca2+ phenotype." (PMID 34810264, 2021). "This has also been observed in claudin-2 and claudin-12 double-KO mice, despite more severe hypercalciuria, and raises the intriguing question of whether claudin-2 in the PT is needed in some way for 1-hydroxylation of 25-hydroxyvitamin D." (PMID 41066193, 2025). "Despite this, inducible claudin-2 KO had robust hypercalciuria." (PMID 41066193, 2025). "Similarly, adult-onset tubule-specific deletion of Cldn2 also produced only transient hypercalciuria." (PMID 41321305, 2025). "Furthermore, DKO mice have even greater hypercalciuria than the single-Cldn2 KO animals." (PMID 34810264, 2021). "We used the hypercalciuric Cldn2 KO mouse model, lacking proximal tubule calcium reabsorption, and mice fed the vitamin D analog, DHTS, which causes hypercalcemia and hypercalciuria." (PMID 36227903, 2022). "Cldn2 KO but not Cldn12 KO mice have hypercalciuria, although direct measurement of perfused proximal tubules from Cldn12 KO mice confirm reduced Ca2+ permeability." (PMID 34810264, 2021). "Why claudin-2 KO mice demonstrate hypercalciuria and claudin-12 null mice do not is unclear, but is perhaps due to a greater abundance of claudin-2 in the proximal tubule." (PMID 32197346, 2020). "However, in contrast to claudin-2–KO mice, mice with genetically defective calcium reabsorption in the thick ascending limb and distal convoluted tubule have little or no nephrocalcinosis despite much more severe hypercalciuria." (PMID 41066193, 2025).
malnutrition (6 papers, 2016 to 2023). Inadequate nutrition resulting from poor diet, malabsorption, or abnormal nutrient distribution. "Claudin-2 knockout can cause defects in paracellular Na+ flow and nutrient transport in the intestine and result in death from malnutrition." (PMID 36902147, 2023). "In a later article, Wada and colleagues reported that mice with the double knockdown of claudin-2 (Cldn-2) and claudin-15 (Cldn-15) genes had impaired paracellular Na+ flow and subsequent malnutrition, leading to infant death." (PMID 35203499, 2022). "Additionally, mice with a double knockout of Cldn2 experienced defective paracellular Na+ and nutrient transport in gut and died from malnutrition, suggesting that alterations in only a few cell junction genes can make a lethal impact on individuals." (PMID 31084603, 2019). "Indeed, it has been shown that claudin-2 and claudin-15 double-knockout mice die as a result of malnutrition in early infancy, suggesting that claudin-2 could also be contributing to Na+-dependent nutrient absorption." (PMID 31936130, 2020). "Genetic susceptibility due to genetic mutations particularly in SPINK1, CFTR, CTRC, and CLDN2/MORC4 genes is the most important factor and not malnutrition or dietary toxins for idiopathic CP suggesting the term ‘tropical pancreatitis’ is a misnomer." (PMID 29868209, 2016).
breast tumors (5 papers, 2015 to 2021). "Contrary to this, our study showed that coexpression of Claudin-2 and Afadin in primary breast tumors is associated with poor clinical outcomes, including increased risk of developing soft tissue-specific metastases (the liver and lungs)." (PMID 30692208, 2019). "Claudin-2 expression in primary breast tumors is prognostic for the development of liver metastases." (PMID 30692208, 2019).
dysplasia (5 papers, 2009 to 2023). A usually neoplastic transformation of the cell, associated with altered architectural tissue patterns. "Claudin-2 expression level can be increased by the activation of IL-6, and increased claudin-2 level enhances IBD-associated dysplasia and sporadic adenomas." (PMID 35865942, 2022). "In summary, we conclude that Claudin-2 expression is significantly increased from normal squamous mucosa to columnar cell metaplasia, BE, low- and high-grade dysplasia to EAC." (PMID 28212604, 2017). "In dysplasia the claudins Cldn2, Cldn4 and Cldn8 were significantly up-regulated, their expression ranged from 4.6–13.31-fold and 4.9–122.38-fold, when transgenic but healthy and non-transgenic lung tissue were compared, respectively." (PMID 19529782, 2009). "For example, a gradual increase was observed in claudin-2-positivity in various stages of gastric carcinogenesis from no expression in gastritis to elevated expression in dysplasia and gastric intestinal-type adenocarcinoma." (PMID 31726679, 2019).
irritable bowel syndrome (5 papers, 2013 to 2025). Irritable bowel syndrome (IBS) is a chronic functional condition of the lower gastrointestinal (GI) tract characterized by abdominal pain or discomfort and disordered bowel habit (diarrhea, constipation, or fluctuation between the two). "Although we do not have an explanation for this phenomenon at this time, an increased expression of another tight junction protein, claudin-2, in association with mast cell activation, has been reported in irritable bowel syndrome patients." (PMID 29685134, 2018). "In irritable bowel syndrome, the expression of miR-125b-5p and miR-16 is downregulated, leading to increased expression of ZO-1 and Cldn2, and consequently impairing intestinal epithelial barrier function." (PMID 40940777, 2025). "Claudin-2 expression was the same in cecum and rectal mucosa of control and diarrhea-predominant irritable bowel syndrome patients." (PMID 28366996, 2017). "Claudin-2 expression was high in the ileum of diarrhea-predominant irritable bowel syndrome patients." (PMID 28366996, 2017). "In addition, we also observed the increase in the expression of Cldn2 in the colon epithelial cells of patients with irritable bowel syndrome." (PMID 23840363, 2013).
Obesity (5 papers, 2017 to 2025). Accumulation of substantial excess body fat. "Overall, our findings highlight for the first time, in our knowledge, clinical significance of claudin expression, especially claudin-2, and tight junction restructuring in dealing with the obesity-associated epidemic." (PMID 28698546, 2017). "We determined whether underlying obesity caused an alteration of tight junction proteins in the distant ileum by Claudin-2 and Occludin immunofluorescence analysis." (PMID 32927823, 2020). "Therefore, we further examined specific signaling mechanisms underlying obesity-induced changes in claudin-2 expression." (PMID 28698546, 2017). "Thus, the possibility that the reduced renal claudin-2 expression may impact blood Na+ -levels by waning proximal tubular reabsorption to aid to obesity-associated co-morbidities including hypertension cannot be ruled out." (PMID 28698546, 2017). "In the light of our in vivo data that obesity resulted in significant suppression of renal claudin-2 expression, contrasting the sharp increase in the intestinal epithelium, we examined if leptin and/or DCA exposure may have similar effects in vitro." (PMID 28698546, 2017). "Furthermore, obesity-induced gut dysbiosis might increase intestinal permeability, which can be measured by increased levels of intestinal claudin-2, serum FITC-dextran or serum LPS." (PMID 34359902, 2021).